NAMPT (nicotinamide phosphoribosyltransferase)
Diseases named in the same sentence as NAMPT in open-access papers (continued):
Sharing a sentence is not in itself a finding about the gene and the disease.
tumor (continued). "Inhibitors for GLUT and NAMPT have been examined as anti-tumor agents for some time already." (PMID 36900207, 2023). "Therefore, at present, it has to be assumed for STF-31 that its favored mode of action depends on the gene expression level of GLUT1 and NAMPT in tumor cells." (PMID 36900207, 2023). "The tumor population showed intracytoplasmic NAMPT expression in all samples." (PMID 36899911, 2023). "Moreover, NAMPT, which is downstream of G-CSF (CSF3) receptor signaling, promotes the tumorigenic conversion of tumor-associated neutrophils (TANs), enhancing angiogenesis via SIRT1 activity." (PMID 38116009, 2023). "In this study, we showed that the novel NAMPT inhibitors delayed or eradicated the tumor growth and thus significantly prolonged xenografted mouse survival, without evident signs of toxicity including loss of body weight, lethargy, rough coat or premature death." (PMID 36838885, 2023). "High NAMPT expression is associated with enhanced NAD+ biosynthesis, which may lead to advantages in tumor cell proliferation and survival." (PMID 37954600, 2023). "In the attempt to explain the lack of efficacy in clinical trials, recent studies demonstrated that gut microbiota and metabolites available in the tumor environment could greatly contribute to counteracting the antitumor activity of NAMPT inhibitors." (PMID 36765744, 2023). "Interestingly, tumor-secreted protein NAMPT acts as a rate-limiting enzyme in the upstream pathway of SIRT1, which restricts the OXPHOS of aged neutrophils (CD45+CD11b+Ly6G+CXCR4+CD62Llo) and prolongs the lifespan of neutrophils by mitophagy." (PMID 38023616, 2023). "These immunotherapy approaches may indirectly upregulate IFN-inducible NAMPT in tumors cells, and we hypothesize that their efficacy can be enhanced by combining these therapies with NAMPT inhibitors that specifically target tumor cells." (PMID 36900204, 2023). "However, they have failed so far as an anticancer therapy in clinical trials also because most tumor cells can elude NAMPT blockade by exploiting alternative NAD-producing pathways." (PMID 37259338, 2023). "Together, these observations implicate increased sensitivity to immune checkpoint blockade therapy and the IFNs induced by immune checkpoint blockade therapy with tumor cell-specific NAMPT inhibition, yet it may depend on the tumor type." (PMID 36900204, 2023). "Notably, NAMPT inhibitors can reduce PD-L1 and B7-H3 expression in tumor cells, indicating their potential as targeted therapeutics for immune therapy." (PMID 35515130, 2022). "Silencing NAPRT in tumor cells could restore the therapeutic efficacy of NAMPT inhibitors even in the presence of bacteria and NAM." (PMID 35396381, 2022). "Varying proteins found in several tumor types in other molecular pathways have recently emerged as potential biomarkers to indicate which candidates may benefit the most from NAMPT inhibition." (PMID 35814452, 2022). "Therefore, NAMPT is usually overexpressed in these tumours since their cells rely on its activity to meet the demands for NAD+." (PMID 36078035, 2022). "GMX1778 phosphorylated by NAMPT accumulates inside tumour cells, enhancing its antitumor effect." (PMID 36078035, 2022). "Additionally, our results on fibroblasts, paved the way to further studies to consolidate the notion to consider NAMPT a novel proto-oncogene in tumor." (PMID 35272691, 2022). "NAMPT expression can be regulated by different inflammatory signals in several types of tumor and immune cells, and, in turn, eNAMPT increases the levels and the release of pro-inflammatory cytokines IL6, IL10, IL1β, and tumor-necrosis factor-α (TNF-α) from leucocytes." (PMID 36077374, 2022).
tumor (continued). "However, high levels of SIRT1 were found in some tumours, in which NAMPT activates SIRT1 expression by increasing NAD+ levels and decreasing NAM." (PMID 36078035, 2022). "The selective vulnerability of IDH1R132H cells to knockdown of NAMPT and NMRK1 indicated that these cells used both pathways to synthesize NAD+, making both enzymes possible targets for the selective treatment of IDH1 mutated tumor cells." (PMID 35628596, 2022). "However, some studies have found that NAMPT can also inhibit tumor migration and metastasis by regulating SIRT-1, indicating that the mechanism remains to be further explored." (PMID 35906622, 2022). "Different neoplasms have exhibited unique expression profiles which may indicate how sensitive each unique tumor would be to NAMPT inhibition." (PMID 35814452, 2022). "Conversely, ectopic NAMPT expression increased tumor growth." (PMID 35565188, 2022). "All these data, taken together, therefore, show that NAMPT inhibitors may be considered dual agents that act on the tumor and on the microenvironment." (PMID 32477131, 2020). "In addition to important effects on cellular metabolism, NAMPT has also been found to participate in a variety of oncogenic cellular processes, including tumor proliferation, apoptosis, metastasis, inflammation, DNA repair and angiogenesis." (PMID 32005247, 2020). "Additionally, NAMPT was upregulated in some malignancies and its expression was correlated with tumor invasion, metastatic potential, and drug resistance." (PMID 32752274, 2020). "If NAMPT could regulate Wnt/β-catenin pathway, then targeting NAMPT such as using its inhibitor FK866 could be a potential therapeutic option to retard tumor growth." (PMID 32005247, 2020). "Our study suggests that the concomitant reduction of NAMPT and PARP-1 activities in CDA-deficient tumor cells may be associated with a better prognosis." (PMID 32807821, 2020). "In this study, we aim to determine the expression of NAMPT in a large cohort of resected stage I/II PDAs using tissue-microarrays (TMAs) constructed at the University of Iowa and to correlate tumor NAMPT expression with overall survival (OS) and recurrence-free survival (RFS) of patients with PDAs." (PMID 30856230, 2019). "In addition to the effect of NAMPT on primary tumor cells, recent insights have begun to elucidate the impact of NAMPT on the immune suppressive characteristics of the tumor microenvironment." (PMID 32010616, 2019). "Based on our observations that mutant PPM1D blocks this pathway via tumor-specific NAPRT silencing, NA supplementation may be an effective approach to further enhance the therapeutic index associated with NAMPT inhibition." (PMID 31439867, 2019). "This study shows that IFN-deficiency leads to the elevated NAMPT expression in the bone marrow, which in turn modulates neutrophil development and differentiation, even in the absence of tumor-derived stimuli." (PMID 31717318, 2019). "Closely monitoring the metabolic adaptations of a tumor to NAMPT inhibition could be useful to inform therapeutic decisions." (PMID 29541451, 2018). "If NAMPT is to be a viable target for drugs to prevent CIPN, it is critical to determine whether stimulation of NAMPT with P7C3-A20 enhances tumor growth or whether it interferes with the anticancer activity of PTX." (PMID 29125463, 2017). "However, NAMPT-underexpressing cells showed clear reductions in the CD133+ and CD44+ pools, confirming that NAMPT is a factor that facilitates tumor cell de- differentiation to a pluripotent-like state." (PMID 29245920, 2017). "Because NAMPT induces the CIC phenotype, we tested whether tumorspheres, as in vitro surrogates for tumor CICs, respond to the NAMPT inhibitor FK866." (PMID 29245920, 2017). "The NAMPT-overexpressing cells grew faster than the parental cells, indicating that NAMPT confers a proliferative advantage, while the NAMPT-underexpressing cells grew slower than the parental cells, confirming the role of NAMPT in tumor proliferation." (PMID 29245920, 2017).
tumor (continued). "In addition, FACS analysis of tumor cells showed higher stem cell phenotypic marker expression, which correlated with NAMPT expression." (PMID 29245920, 2017). "Therefore, the efficiency of NAD+ depleting drugs, such as NAMPT inhibitors, when used alone are expected to be low due to insufficient tumor-selectivity." (PMID 27462772, 2016). "In particular, evidence on how is NAPRT expression regulated in tumor cells could spark developments to expand the use of NA cytoprotective therapies in treatments using NAMPT inhibitors." (PMID 26675378, 2016). "Interestingly, NAMPT inhibition sensitizes pancreatic adenocarcinoma cells to tumor-selective, PAR-independent metabolic catastrophe and cell death induced by β-lapachone and FK866 led to either tumor regression or stabilization in a preclinical trial." (PMID 27462772, 2016). "Accordingly, NAMPT inhibitors show stronger cytotoxity on tumor cells compared with normal cells." (PMID 26227784, 2015). "APO866 is a new anti-tumor compound inhibiting nicotinamide phosphoribosyltransferase (NAMPT)." (PMID 23308217, 2013). "Results indicate that mouse NAMPT is highly expressed in the luminal epithelium-derived tumor cells with highly expanded tubular, adenoid cystic and papillary tumor tissue structures (orange staining), and that FGFR4 deficiency attenuates the NAMPT levels." (PMID 24279986, 2013). "Notably, although xenograft tumours from NAMPT inhibitor-resistant derivatives of HCT-116 were found to contain many necrotic areas, similar results were observed for parental HCT-116 cells." (PMID 21144000, 2010). "Importantly, OV had the lowest p-value rank, suggesting that elevated NAMPT expression may promote tumor growth by increasing NAD+ production in the OV." (PMID 40280967, 2025). "Moreover, NAMPT-mediated NAD+ levels were found to positively regulate T cell anti-tumor function." (PMID 40846839, 2025). "Additionally, elevated NAMPT expression is associated with poor patient prognosis but is independent of tumor staging." (PMID 40463392, 2025). "Indeed, there is evidence that in some tumor types, elevated NAPRT expression may be associated with insensitivity to NAMPT inhibition." (PMID 40342733, 2025). "Importantly, NAMPT inhibition is effective in both 2D and 3D models, which are becoming increasingly useful when performing experiments in vitro, as they better represent intact tumours." (PMID 38893173, 2024). "In a real life situation, where many NAD+ precursors could be present in a tumor environment, blocking only one pathway of NAD+ synthesis would not be sufficient and this could greatly contribute to the loss of the therapeutic efficacy of NAMPT inhibitors." (PMID 36838885, 2023). "Besides NAMPT, enzymes of the metabolic pathway are perfect targets to inhibit tumor growth." (PMID 36901897, 2023). "Notably, tumors treated with the NAMPT inhibitor showed a significative reduction of the tumor volume, which reached an inhibition of about 70% starting from Day 17, and, more interestingly, a stabilization of the disease was observed and maintained for ~20 days following the end of the treatment." (PMID 37858982, 2023). "The level of NAD+ precursors may considerably affect the anti-tumor efficiency of NAMPT inhibitors." (PMID 35396381, 2022). "In addition, new NAMPT inhibitors have been conjugated with antibodies, which are called ADCs (antibody–drug conjugates), with the aim of specifically targeting the drug to the tumour while avoiding damage to healthy tissues." (PMID 36078035, 2022). "In addition, the role of NAMPT in regulating the tumor microenvironment has been addressed." (PMID 35565188, 2022). "Furthermore, recent insights have revealed several additional targetable cellular processes that are impacted by inhibition of NAMPT, such as—sirtuin function (tumor cell proliferation and progression), DNA repair machinery, redox homeostasis (ROS), and immune processes." (PMID 36497496, 2022).
tumor (continued). "However, the utility of the same will depend on the expression levels of GLUT1 and NAMPT, which may vary in a tumor-to-tumor manner." (PMID 36386187, 2022). "However, increasing evidence suggests that a better selection of tumor subtype rely exclusively on NAMPT activity to generate NAD, as well as novel drugs less toxic, could open a second life for NAMPT inhibition strategy." (PMID 34421911, 2021). "Furthermore, overexpressed NAMPT levels were associated with poor patient prognoses, independent of tumor stage." (PMID 33384409, 2021). "We first assessed several human macrophage cell lines, which all responded to IFNγ by upregulating NAMPT expression, in parallel with the positive control IFNγ target CXCL10, leading us to investigate a role for this metabolic enzyme in regulating human tumor-associated immune responses." (PMID 33976173, 2021). "Perhaps, a combination approach with tumor-selective DNA damaging agents (e.g., NQO1-bioactivatable agents, vide infra in Section 6) may overcome this limitation to improve the tumor-selectivity of NAMPT inhibitors by severely depleting the NAD+ needed by PARPs for efficient DNA repair and survival." (PMID 32295316, 2020). "In addition to its function in cellular energy metabolism, NAMPT is involved in sirtuin function, support of DNA repair mechanisms, maintenance of redox balance, molecular signaling, determination of cellular states, and tumor-related immune suppression." (PMID 32010616, 2019). "This may explain the changes in bone marrow composition in type I IFN deficiency, which correlates with the upregulation of NAMPT signaling, even in the absence of tumor-derived stimuli." (PMID 31717318, 2019). "Finally, the key mechanism of action of NAMPT inhibition is the blockade of glycolysis at the glyceraldehydes-3-phosphate dehydrogenase step responsible for adenosine triphosphate (ATP) depletion, metabolic perturbation, and subsequent tumor growth inhibition." (PMID 25486521, 2014). "For instance, it has been shown that the decrease in NAD+ levels, obtained by inhibiting with shRNA the expression of NAMPT, could make tumor cells more aggressive, while the treatment with FK866, that targets the same enzyme, leads to cancer cell death both in vitro and in vivo." (PMID 25476909, 2014). "Whilst we have focused upon the effect that NAMPT inhibition can have on DNA damage biomarkers such as nuclear γH2AX foci formation, it is also possible that NAMPT inhibition could also impinge upon other mechanisms that other tumour cells are reliant upon." (PMID 22933245, 2012). "Nicotinamide is also a substrate of nicotinamide phosphoribosyltransferase (NAMPT) that converts it to nicotinamide adenine dinucleotide (NAD+), whose 15N-labeled fraction accounted for ~24% of the total pool in the tumor tissue." (PMID 41576167, 2026). "Extracellular NAMPT, functioning independently of its enzymatic NAD synthesis role, acts as an cytokine that promotes inflammation and tumor progression through pathways involving MAPK, NF-κB, and PI3K/Akt signaling cascades." (PMID 40282553, 2025). "Further transcriptomic analysis of TCGA GBM samples revealed a positive correlation between NAMPT expression and epithelial-to-mesenchymal transition (EMT) markers, suggesting a link between NAMPT and a mesenchymal tumor phenotype." (PMID 40563807, 2025). "As expected, the addition of nicotinamide mononucleotide (NMN), a derivative of NAM, rescued the anti-tumor effect of GNE-617 across all cell lines, since this molecule is downstream of NAMPT in the salvage pathway." (PMID 40280967, 2025).
tumor (continued). "Specifically, enhanced NAMPT expression promotes NAD+ and ATP metabolic reprogramming, which is critical for filopodia formation and tumor metastasis." (PMID 40775221, 2025). "Nicotinamide phosphoribosyltransferase (NAMPT) is the rate-limiting enzyme for nicotinamide adenine dinucleotide (NAD) and has been reported to play a critical role in tumor cell proliferation as a direct target of the BRAF oncogenic signaling pathway." (PMID 40724826, 2025). "We have observed that, in other tumor models, NAMPT downregulation reduces the tumorigenicity and CSC-like properties of tumor cells." (PMID 40805270, 2025). "Recent findings suggest that targeting NAMPT can inhibit SIRT1 signaling and neutrophil angiogenic gene transcription, offering a potential mechanism for tumor growth inhibition." (PMID 39925807, 2025). "NAMPT-mediated NAD+ salvage dictates mitochondrial homeostasis and oxidative phosphorylation activity, supporting the optimal anti-tumor immunity of immune cells." (PMID 40775221, 2025). "Because of the multifaceted and pathway-connecting role of NAD in the cell, the rate-limiting enzyme for NAD synthesis, nicotinamide phosphoribosyl transferase (NAMPT), has been identified as a target for tumor therapy." (PMID 38225236, 2024). "In the tumor tissue stage, monocytes remain active in the TME, interacting with tumor cells and other immune cells, marked by elevated expression of CXCL8, NAMPT, AQP9, and BCL2A1." (PMID 38720887, 2024). "To further investigate the effect of LZFPN-90 on tumor cells, we selected three cell lines (A2780, HCT-116, LLC) with different expressions of NAMPT to investigate the inhibitory effect of LZFPN-90 on their proliferation." (PMID 38448544, 2024). "STF-31 not only inhibits NAMPT, but also inhibits GLUT1, showing an inhibitory effect on tumor cells." (PMID 39513038, 2024). "The variability in the expression of different NAD biosynthetic enzymes and sensitivity to NAMPT inhibition is consistent with the well-established interheterogeneity and intraheterogeneity across GBM tumours from different patients." (PMID 38893173, 2024). "Elevated NAMPT levels enhance SIRT1-mediated deacetylation and FOXO3a expression, providing protection against oxidative stress and supporting tumor resilience." (PMID 39796040, 2024). "FK866, is the earliest discovered NAMPT inhibitor, which selectively inhibits NAMPT, resulting in a decrease in NAD+ levels, and then inhibiting the growth of tumor cells." (PMID 39513038, 2024). "CHS828 acts as a competitive inhibitor of NAMPT, decreasing the cellular level of NAD+ and resulting in cell death and tumor regression." (PMID 39272943, 2024). "The NAMPT inhibitor FK866, which induces NAD depletion, has shown promise in controlling tumor proliferation and modifying the tumor microenvironment." (PMID 39336077, 2024). "It has been reported that tumor cells consume NAD+ at a faster rate than normal cells, displaying very active metabolism, and expressing high levels of NAMPT to satisfy the high demand for NAD+." (PMID 38448544, 2024). "In this study, by investigating the link between NAMPT and PD-L1, we identified a relationship between tumor NAD+ metabolism and tumor immune escape." (PMID 38448544, 2024). "Here, we examined a key nexus of IFNγ-mediated tumor cell fitness, metabolic reprogramming by upregulating the essential nicotinamide adenine dinucleotide (NAD+) salvage pathway enzyme, nicotinamide phosphoribosyltransferase (NAMPT)." (PMID 36900204, 2023). "This further verified that NAMPT and ACAT1 play biological roles mainly by regulating the energy metabolism of various cell types, whereas IDO1 affects tumor progression by regulating the activity of immune cells." (PMID 37954600, 2023). "Further, NAMPT expression in CD8+ T cells is necessary to produce NAD+ and induce anti-tumor effects." (PMID 37842241, 2023).